MIR652 (microRNA 652)
Synonyms: hsa-mir-652; MIRN652
Gene: MicroRNA gene on chromosome X (110,055,329 to 110,055,426, forward strand). Ensembl gene ENSG00000208013.
Gene Ontology:
Biological process: miRNA-mediated post-transcriptional gene silencing
Homologues: Orthologues: chimpanzee ptr-mir-652 (100% identical), macaque mml-mir-652 (99% identical), pig MIR652 (99% identical), guinea pig MIR652 (95% identical), rabbit MIR652 (94% identical), mouse Mir652 (92% identical), rat Mir652 (81% identical), dog MIR652 (64% identical).